JAK3 (Janus kinase 3)
Diseases named in the same sentence as JAK3 in open-access papers (continued):
Sharing a sentence is not in itself a finding about the gene and the disease.
tumor (continued). "Second, HOTAIR down-regulates the expression of E-cadherin and miR-217, then activates the DACH1/JAK3/STAT3 and Wnt/β-catenin pathways, which are involved in the tumor’s EMT ability, which is important for primary tumor formation and metastasis." (PMID 36924407, 2023). "JAK3/STAT signaling drives the expression of oncogenic miRs such as miR-155, miR-21, miR-93, and miR-214 as well as repression of putative tumour suppressors (SATB1, PDCD4, JARID2) in malignant T cells." (PMID 33466582, 2021). "We have observed significant upregulation of IFNG, JAK3, STAT1, and STAT2 in tumor compared to normal samples." (PMID 33980865, 2021). "On the other hand, JAK3 is ectopically expressed in various CTCL cell lines and tumor cells in the blood of SS patients." (PMID 34681738, 2021). "As expected, the mRNA levels of JAK3 were significantly increased in STAD during subgroup analyses based on the race, gender, age, H. pylori infection status, histological subtype, tumor grade, cancer stage, and nodal metastasis status of patients." (PMID 33083484, 2020). "JAK3/TYK2 levels were significantly increased in STAD during subgroup analyses based on gender, tumor grade, cancer stages, and nodal metastasis status." (PMID 33083484, 2020). "Previous studies have also clarified the significant role of JAK3 and TYK2 in the tumor microenvironment and immune response." (PMID 33083484, 2020). "In this study, we found that the expression levels of JAK3 and TYK2 were higher in tumor tissues than in normal tissues in STAD." (PMID 33083484, 2020). "Tumor-derived EVs from tumor patients can down-regulate health of CD3ζ donors, which is part of the T-cell antigen receptor and JAK3 (Janus kinase 3) expression in T cells." (PMID 31795140, 2019). "We found ten potential prognostic genes, including eight tumor suppressor and/or driver genes (VEGFA, CCND1, BAX, IL7R, SHC1, FLT1, IL7, and JAK3), as well as two chemokines (CXCL9 and CXCL10)." (PMID 31661791, 2019). "For example, several kinases with consistently more signal in the tumor samples relative to the matched controls include: AurA, CHED (CDK13), JAK3, p38α, CHK1, ITPK." (PMID 27031502, 2016). "Among the loci displaying >95% specificity (that is, very low DNA methylation frequency in normal tissue), the frequency of hypermethylation in tumor tissue ranged from 28% (DBC1, deleted in bladder cancer 1) to 75% (JAK3, Janus kinase 3)." (PMID 20920229, 2010). "Inhibitory effects of tumor-shed PGE2 were in fact dependent on impairment of IL2Rγc signaling that lead to down regulation of IL2Rγc, reduced phosphorylation of Jak-3 and Stat-5A and decreased expression of pro-survival protein Bcl-2." (PMID 19812686, 2009). "JAK1 and JAK3 were more expressed in the tumor stage than patch and plaque stage MF, suggesting that JAK1 and JAK3 could play a crucial role in MF pathogenesis, progression, and prognosis." (PMID 41806757, 2026). "Notably, these same malignant T cells also express LTα, whose production is induced by dysregulated JAK3/STAT5 signaling, thereby contributing to IL-6 secretion and synergizing with VEGF to support tumor vascularization." (PMID 41171472, 2025). "We hypothesized that this monocyte subset (JAK3+TLR4+ CD16 monocyte) contributes to shaping pro-tumor immunity in TME, ultimately accelerating malignant transformation and tumor progression." (PMID 38149248, 2023). "Served as family member of non-receptor protein-tyrosine kinases, Janus kinases (JAKs) consists of JAK1, JAK2, JAK3, and tyrosine kinase-2 (TYK2), they behave pivotal roles in cytokine pathways and are closely related to both inflammatory and neoplastic diseases." (PMID 38095643, 2023). "In multiple cancer models, azaspirans and their derivatives have been tested as inhibitors of some tyrosine kinase proteins related to tumor progression, such as atiprimod (JAK2/JAK3 inhibitor) and lestaurtinib (JAK2 inhibitor), which present different tumor inhibition mechanisms." (PMID 37299000, 2023).
tumor (continued). "Additionally, in CD16 monocytes, the remaining NPA genes, JAK3, PPIA, and TLR4 were up-regulated in tumor tissues, while IFNGR1 was down-regulated in tumor samples." (PMID 38149248, 2023). "The functions of FOXP3, JAK3, and IKZF3 are widely researched in the field of tumor immunology." (PMID 35719936, 2022). "An anti-proliferative role of OSM was reported in immune-deficient mice injected with human melanoma cells and in a chondrosarcoma model, where local intra-tumor overexpression of OSM reduced tumor development and enhanced tumor cell apoptosis through the JAK3/STAT1 axis." (PMID 36077744, 2022). "LMP-1 activates the Janus kinase 3 (JAK3)/Signal transducer and activator of transcription 3 (STAT3) pathway, which increases the expression of vascular endothelial growth factor (VEGF) and promotes tumor metastasis and invasiveness." (PMID 32194785, 2020). "The same results were obtained for TYK2, and the mRNA levels of JAK3 were significantly increased in STAD during subgroup analyses based on the race, gender, age, H. pylori infection status, histological subtype, tumor grade, individual cancer stage, and nodal metastasis status of patients." (PMID 33083484, 2020). "Previous studies have reported that inhibition of the JAK3/STAT5 pathway induced apoptosis of tumor cells; however, its effect on the cell cycle has not been fully investigated." (PMID 27732937, 2016). "Taking into account the cases of the WES cohort and the additional eight cases with targeted sequencing, interestingly, the two tumours with no alterations in SETD2 (case 13 and case 6) both harboured concurrent mutations in JAK1 and JAK3." (PMID 27600764, 2016). "Notably, the IL2/JAK3/STAT5 axis has been reported critical for inflammatory responses, and plays key roles in immune‐related pathological processes in cancer, such as contributing to cancer‐related pain, tumor cell survival and T‐cell exhaustion." (PMID 38545256, 2024). "We showed that by treating U87 and U251 GBM cells with two specific JAK3 inhibitors, WHI-P131 and PF-956980, JAK3 activity could be significantly downregulated, and this has tremendous beneficial effects in preventing tumor cell proliferation and inducing cellular differentiation." (PMID 37947625, 2023). "Indeed, tumor-shed PGE2 down-regulates IL2Rγc expression, reduces phosphorylation as well as activation of Janus kinase 3 (Jak-3)/signal transducer and activator of transcription 5 (Stat-5) and decreases Bcl-2/Bax ratio thereby leading to activation of intrinsic apoptotic pathway." (PMID 19812686, 2009). "Thus, JAK3 promotes survival and proliferation of malignant T cells and expression of proto-oncogenes/oncomiRs and cytokines (IL-5, IL-9, IL-13, IL-17F and LTA), some of which are growth factor to malignant T cells while others modulate the tumour micro-environment (TME) and anti-cancer immunity." (PMID 33466582, 2021). "Moreover, we observed that immune‐related and cell adhesion‐related genes such as CD83, HLA‐DRA, JAK3, CEACAM6, and ITGB238, 39, 40, 41 exhibited high H3K27me3 modification in tumour cells, suggesting that their expression may be suppressed by H3K27me3 to facilitate immune escape of tumour cells." (PMID 39210544, 2024). "Chemotaxis is also involved in the “Role of tumor-infiltrating B cells in anti-tumor immunity” pathway map and includes BTK and JAK3, but does not include ITK." (PMID 34803999, 2021).
cancer (112 papers, 2009 to 2026). A tumor composed of atypical neoplastic, often pleomorphic cells that invade other tissues. "Past cancer studies investigated the transforming role of JAK3 mutations and their capacity to disrupt aberrant activation using selective inhibitors such as CP-690,550." (PMID 37569303, 2023). "Mutations were found most frequently in three genes, STAT3, BCOR and MLL2 (which were present in nine, seven and six cancer samples, respectively), whereas there were only two cases of Janus kinase 3 (JAK3) mutation." (PMID 26146524, 2015). "Mutations were found most frequently in 3 genes, STAT3, BCOR, and MLL2 (which were present in 9, 7, and 6 cancer samples, respectively), whereas there were only 2 cases of JAK3 mutation." (PMID 25980440, 2015). "JAK3 is an enzyme in the janus kinase family and has been implicated in cell signaling processes important in cancer and immune-inflammatory diseases." (PMID 24337368, 2014). "JAK3 copy number changes were also evident with copy number gain most prevalent in adenoma/adenocarcinoma, ovarian cancer and glioblastoma, while copy number loss was highest in cancers of the bronchus and lungs." (PMID 38474223, 2024). "JAK3 mutations exclusive to SHiGDA suggest failure of immune surveillance by the gutassociated lymphoid tissue [GALT] to recognize the malignant potential of SHiGDA allowing unimpeded progress to infiltrative cancer." (PMID 39507544, 2024). "Mutated JAK3 has been considered a promising target for cancer therapy." (PMID 35111683, 2021). "Collectively, this indicates that small‐molecule inhibitors targeting JAK3 may be an effective therapeutic intervention in several cancers and immune‐related diseases caused by persistently activated JAK3 signalling." (PMID 32558259, 2020). "Inhibiting JAK3 with tofacitinib was, and still is, clearly an attractive option in transplantation with a low incidence of rejection, no nephrotoxicity, and better histological preservation but a safety profile that was not ideal for low to moderate risk patients (more infections and cancers)." (PMID 24565406, 2013). "Cancer-related genes such as JAK3 and VIM were upregulated with the increased level of trait-associated genes in spots." (PMID 41123022, 2026). "The mRNA levels of JAK3 also demonstrated a positive correlation with the functional module of NK cell effector functions across various human cancer types, as indicated by data from the TCGA and GTEx databases." (PMID 40486832, 2025). "Janus kinase 3 (JAK3) is a hematopoietic-specific kinase implicated in cytokine signaling and immune dysregulation and has recently been associated with cancer progression." (PMID 41385500, 2025). "In this study, we established a machine learning (ML)-based pipeline to identify novel JAK3 inhibitors with anti-cancer potential." (PMID 41385500, 2025). "Because cytokine signaling pathways are frequently dysregulated in cancer cells, JAK3 plays a part in cancer." (PMID 40872614, 2025). "JAK3 is a significant negative regulator in cancer cell viability and apoptosis by regulating various downstream factors, such as STAT3, Akt and PS6K." (PMID 39991585, 2025). "Conversely, the zebrafish JAK3 LOF model can be applied as a xenotransplantation platform to examine JAK3 GOF-mediated cancers in a patient-specific manner, underpinning the development of patient-centered therapeutic approaches." (PMID 38474223, 2024). "JAK-3, a cancer protein, also known as the JAK3 gene is a stable well-binding protein of the ginkgetin which has a well confirmed stereochemistry and is a high-quality structure with 90% residue in its most favored region." (PMID 37720295, 2023).
cancer (continued). "The JAKs protein family is composed of four isoforms, and JAK3 has been regarded as a druggable target for the development of drugs to treat various diseases, including hematologic tumors, cancer, and neuronal death." (PMID 37886358, 2023). "BTK and JAK3 are two important enzymes that can be potentially targeted to inhibit downstream signaling pathways related to cancer cell growth." (PMID 37894618, 2023). "Among them, ARID1A, TSC2, JAK3, CIC, CINNB1, and SETD2 were mutated at the early stage of carcinogenesis, which played an essential role in advancing early cancer development and progression." (PMID 35795211, 2022). "In a word, morphine in combination with ketamine improves cancer pain and suppresses immune function via the JAK3/STAT5 pathway." (PMID 35492074, 2022). "Pan-cancer analysis identified IKZF3, FOXP3, and JAK3 had a similar distribution and effects in HPV-associated HNSC." (PMID 35719936, 2022). "In this study, the therapeutic effect of morphine combined with ketamine on cancer pain for CC patients and the relationships with the JAK3/STAT5 pathway on the regulation of immune functions were investigated." (PMID 35492074, 2022). "The NGS analyses identified mutations in eight cancer associated genes: ESR1, MECOM, JAK3, KMT2C, CTNNB1, CALR, NCOR1 and AMER." (PMID 34209696, 2021). "JAK3 belongs to the Janus kinase family of tyrosine kinases, which are believed to play a key role in oncogenesis and disease progression in several cancers including hematological malignancies." (PMID 33466582, 2021). "Previous reports have demonstrated that treatment with JAK3‐specific inhibitors or siRNA induce apoptotic cell death by blocking JAK3 signalling in persistently JAK3‐activated cancer cells." (PMID 32558259, 2020). "It selectively targeted the kinase activity of JAK3, resulting in inhibition of JAK3 activation and, therefore, suppressed the survival and proliferation of cancer cells that expressed constitutive JAK3 activation." (PMID 32558259, 2020). "We found that somatic genomic alterations of the RECQL4, JAK3, ARID1A, and MAGI1 genes, combined with MBs, were associated with the development of metachronous cancers after curative ESD and successful HP eradiation." (PMID 33328548, 2020). "Tubulosine inhibited the catalytic activity of JAK3 and resulted in a decreased survival and proliferation of cancer cells with persistent JAK3‐activation by inducing apoptotic and necrotic/autophagic cell death." (PMID 32558259, 2020). "Tubulosine effectively reduced the proliferation of cancer cells that persistently expressed active JAK3 signalling in time‐ and concentration‐dependent manners." (PMID 32558259, 2020). "In contrast, the proliferation of cancer cells with non‐JAK3 activation decreased only marginally, even at high concentrations of tubulosine treatment for 72 hours." (PMID 32558259, 2020). "Tubulosine specifically decreased survival and proliferation of cancer cells, in which persistently active JAK3 is expressed, by inducing apoptotic and necrotic/autophagic cell death without affecting other oncogenic signalling." (PMID 32558259, 2020). "As expected, tubulosine significantly reduced the viability of cancer cells that harboured constitutively activated JAK3 signalling in time‐ and concentration‐dependent manners." (PMID 32558259, 2020). "Crosstalk of gas signaling molecules with other signaling pathways such as JUN, JAK2, JAK3, and NF-κB, upregulates p38MAPK, hypoxia, immune cell, and cancer metastasis signaling." (PMID 30972102, 2019). "STAT3, a downstream target of JAK-3, is required for the proliferation and self-renewal of cancer stem cells." (PMID 28289331, 2017). "To demonstrate the selectivity of NSC114792 for JAK3, we also showed that NSC114792 inhibits the tyrosine phosphorylation of JAK3 and decreases cell viability only in cancer cells harboring persistently-activated JAK3." (PMID 20149240, 2010).
cancer (continued). "JAK3 pathway, a vital signaling cascade, can be activated in various cancers, whose activation could promote cancer progression 39-41." (PMID 39991585, 2025). "Some anticancer drugs could induce autophagy and apoptosis by blocking the JAK3 signaling pathway in various cancer cells." (PMID 39991585, 2025). "The continuous stimulation of JAK3 signaling plays a vital role in maintaining malignant tumors." (PMID 39991585, 2025). "Therefore, selective inhibition of JAK3 represents a promising yet underexplored approach in cancer therapeutics, with potential applications extending beyond hematologic malignancies to solid tumors exhibiting aberrant JAK/STAT pathway activation." (PMID 41385500, 2025). "The JAK2 and JAK3 protein kinases that participate in the mediation of cytokine signaling are important drug targets for the prevention or regulation of various types of cancers." (PMID 39339202, 2024). "Furthermore, we investigate covalent interactions between JAK3 and ligands through Cys909, recognizing its vital role in affinity and binding during cancer and RA cell recognition." (PMID 37570884, 2023). "Recent studies suggest that fusion transcripts may participate in constitutive JAK3 activation and promote its downstream signaling pathways of cancer cells." (PMID 37830594, 2023). "Furthermore, because JAK3 is involved in cell proliferation and death, it has the potential to be used in cancer therapy." (PMID 37570884, 2023). "Our finding indicated that morphine-ketamine combination could improve cancer pain and repress immune function via the JAK3/STAT5 pathway in the progression of CC." (PMID 35492074, 2022). "Interestingly, we observed that tubulosine increased the level of ERK1/2 phosphorylation only in JAK3‐harboured cancer cells." (PMID 32558259, 2020). "We further investigated whether tubulosine could inhibit constitutively active JAK3 signalling in various cancer cell lines." (PMID 32558259, 2020). "Increasing evidence demonstrates JAKs as a prognostic biomarker and therapeutic target for many cancers or other diseases, such as JAK3 for renal cell carcinoma, JAK2 for acute lymphoblastic leukemia, JAK2 for skin cutaneous melanoma, and TYK2 for hepatocellular carcinoma." (PMID 33083484, 2020). "Dysregulated JAK/STAT signalling leads to an increase in survival and proliferation of various types of cancer cells, suggesting that tubulosine could decrease viability only in cancer cells harbouring constitutively active JAK3 signalling." (PMID 32558259, 2020). "These genes contain known cancer-related genes such as Jak3, Foxo1, and Cdkn1a (p21)." (PMID 30621584, 2019). "An accumulating data exercise revealed that inhibition of the JAK3 signaling could reduce cancer progression." (PMID 31861050, 2019). "Taken together, this study demonstrated the clinical utility of targeted NGS with a focused hotspot cancer gene panel in NSCLCs and identified activating mutations in JAK2 and JAK3 with clinical implications inferred through integrative analysis of cancer genetic, genomic, and pharmacogenomic data." (PMID 29082853, 2017). "Finally, we showed that NSC114792 decreases cell viability by inducing apoptosis through down-regulating anti-apoptotic gene expression only in cancer cells harboring persistently-active JAK3." (PMID 20149240, 2010). "Because NSC114792 selectively inhibited JAK3/STAT signaling, we hypothesized that treatment with our compound would affect cell viability only in cancer cells that express constitutively-active JAK3/STATs." (PMID 20149240, 2010). "Indeed, it was reported that over-expression of p21 in DU145 cells blocked G1-S progression and that inactivation of JAK3/STAT pathway in cancer cells increased p21 expression." (PMID 19744341, 2009). "Therefore, these compounds are potentialinhibitors for cancer protein JAK-3." (PMID 37720295, 2023).